PTBP1 (polypyrimidine tract binding protein 1)
Diseases named in the same sentence as PTBP1 in open-access papers (continued):
Sharing a sentence is not in itself a finding about the gene and the disease.
rheumatic diseases (1 paper, 2021). "Among these proteins, U1–70K (Snrnp70) is the target of self-reactive B cells and T cells in several rheumatic diseases, Ptbp1 is essential for B cell ontogeny and B cell receptor (BCR)-mediated antibody production, HnrnpL involved in the regulation of TNF α gene transcription." (PMID 35006449, 2021).
squamous cell carcinoma (1 paper, 2022). A carcinoma arising from squamous epithelial cells. "To confirm in vivo that PTBP1 binds to TP63 pre-mRNAs, we immunoprecipitated specifically PTBP1/RNA complexes from keratinocytes (HaCaT) or squamous cell carcinomas cell lines (SCC9) cell extracts and analyzed the pre-mRNA content of the complexes by RT-PCR." (PMID 36970727, 2022).
steatosis (1 paper, 2017). Increased lipid within the cytoplasm of cells. "Ectopic expression of H19 induced steatosis and pushed the liver into a “pseudo fed” state in response to fasting by promoting PTBP1-mediated SREBP1c protein cleavage and nuclear translocation." (PMID 30148159, 2017). "Deletion of H19 or knockdown of PTBP1 abolished high-fat and high-sucrose (HFHS) diet-induced steatosis." (PMID 30148159, 2017).
thymoma (1 paper, 2021). A neoplasm arising from the epithelial cells of the thymus. "Focusing on protein recovery, we determined greatly enriched polypyrimidine tract-binding protein 1 (Ptbp1) RBP compared to the negative control β-tubulin in mRNA capture experiments using the EL-4 thymoma cell line." (PMID 34471108, 2021).
uterine carcinosarcoma (1 paper, 2026). A usually aggressive malignant neoplasm arising from the uterine corpus and less often the cervix. "In uterine carcinosarcoma (UCS), PSI values of KRAS E4 showed the strongest positive correlation with PTBP1 mRNA expression levels." (PMID 41368203, 2026).
viral myocarditis (1 paper, 2023). Myocarditis that is caused by an infection with a viral agent. "In a viral myocarditis cell model, linc-ROR destroyed the mRNA stability of Forkhead Box P Factor 1 (FOXP1) by binding polypyrimidine tract binding protein 1 (PTBP1), promoting coxsackievirus B3-induced cardiomyocyte inflammation." (PMID 36827545, 2023).
cancer (150 papers, 2009 to 2026). A tumor composed of atypical neoplastic, often pleomorphic cells that invade other tissues. "In conclusion, the findings suggest that PTBP1 promotes cancer development by regulating the AS of tumor-associated genes, underscoring the significance of AS as a key regulator of tumor formation." (PMID 40296916, 2025). "The splicing factor polypyrimidine tract binding protein 1 (PTBP1) has been shown to facilitate cancer progression by modulating oncogenic variants." (PMID 40296916, 2025). "To elucidate the molecular mechanism underlying PTBP1’s pro-cancer function, we conducted transcriptomic sequencing on PTBP1-depleted MHCC97H cells and corresponding controls." (PMID 40296916, 2025). "Our analysis revealed that PTBP1 expression is associated with prognosis in nine types of cancer, and its expression can reasonably predict 1-year, 3-year, and 5-year survival rates in seven of these cancer types." (PMID 38918441, 2024). "Further elucidation of the underlying mechanisms governing PTBP1's role in cancer development and progression holds the potential to revolutionize cancer diagnostics and therapeutic interventions in the future." (PMID 38918441, 2024). "In summary, our analysis indicates that PTBP1 expression is a prognostic risk factor in several cancers, including LUAD, KIRP, LIHC, SARC, MESO, LGG, and ACC." (PMID 38918441, 2024). "Overall, our study highlights that immune cell infiltration in most cancers is associated with PTBP1 gene expression." (PMID 38918441, 2024). "We have analysed PTBP1 expression in relation to tumour neoantigens and tumour mutational burden in a variety of cancers." (PMID 38918441, 2024). "Next, we detected key transcription factors associated with cancer stem-cell phenotypes after genetic manipulation of PTBP1." (PMID 36635500, 2023). "It has been previously reported that PTBP1 plays a tumor-promoting role in cancer progression and is associated with cervical lesion progression and carcinogenesis in our former studies." (PMID 36344495, 2022). "Among these transcripts, KIAA1522-a6 had the second largest number of associated anti-cancer drugs, and showed large expression change upon PTBP1 knockdown." (PMID 36357395, 2022). "Our TCGA-based survival analysis results also indicated a correlation between high expression of PTBP1 and poor OS, as well as immune infiltration of cancer-associated fibroblasts." (PMID 36595978, 2022). "We focused on PTBP1, which has been shown to be associated with invasion, metastasis and poor prognosis of cancer." (PMID 35003358, 2021). "As well as Ezh2, among the target genes of miR-124 in cancer cell, polypyrimidine tract-binding protein 1 (Ptbp1; PTB1 gene in humans) is known to be associated with such an effect." (PMID 34072894, 2021). "More interestingly, PTBP1 is associated with the response of cancer cells to chemotherapeutic drugs." (PMID 32207235, 2020). "Currently, a series of researches have demonstrated that PTBP1 is abnormally expressed in cancer tissues or cells and is associated with the pathological processes of cancer development." (PMID 32207235, 2020). "In order to investigate specifically the prognostic value of high PTBP1 expression level, tissues from patients with stageIcolorectal cancer (very low risk of progression) and patients with preoperatively distant metastases (stage IV) patients were excluded." (PMID 28404950, 2017). "Now, we are seeking to elucidate the functions of PTBP1-associated miRs and PTBP1 in many other kinds of cancer cells." (PMID 26980745, 2016). "PTBP1 has been shown to be critical for the generation of pyruvate kinase isoforms and associated aerobic glycolysis in cancer cells (known as the “Warburg effect”)." (PMID 27513449, 2016). "In human tumours, PTBP1 variable splicing abnormalities occur frequently, which may be due to mutations in splicing regulatory elements of specific cancer‐related genes or changes in splicing regulatory processes." (PMID 40579921, 2025).
cancer (continued). "The molecular mechanism by which PTBP1 regulates AS in hepatocarcinoma remains elusive, primarily due to the diverse PTBP1- regulated AS networks implicated in tumorigenesis across different cancer types." (PMID 40296916, 2025). "Additionally, PTBP1 mRNA levels correlate with immune infiltration, mutation burden, treatment response, and prognosis in various cancers." (PMID 41313521, 2025). "In this study, based on multi-omics analysis of the TCGA and CGGA databases, we clarified the relationship between PTBP1 mRNA expression and gene methylation, tumor immune microenvironment, tumor neo-antigen burden, and tumor mutation in various types of cancer." (PMID 38918441, 2024). "In addition, we found that PDCD1 and CTLA4 were also associated with PTBP1 expression in these 3 cancer types." (PMID 38918441, 2024). "PTBP1 has been implicated in cancer development and progress across various tumor types." (PMID 38247832, 2024). "Furthermore, studies have proven that PTBP1 was positively associated with glucose metabolism of cancer cells through modulating the pyruvate kinase M2 isoform." (PMID 37724122, 2023). "In addition, we compared the phosphorylation and immune infiltration of PTBP1 in cancer-associated fibroblasts between normal and primary tumor tissues and explored the putative functional mechanism of tumorigenesis mediated by PTBP1." (PMID 36595978, 2022). "Among the PTBP family members, PTBP1 is most frequently linked with cancer, followed by PTBP3." (PMID 36203873, 2022). "Underscoring the functional relevance of these increases, increased expression of HNRNPA2B1 and PTBP1 has been shown to be responsible for the predominance of the PKM2 isoform that is the hallmark of many types of cancer, promoting the aerobic glycolysis that is important for cell growth." (PMID 20946641, 2010). "Thus, PNCTR may act as a buffer allowing cancer cells to express sufficiently large amounts of PTBP1 while mitigating the risk of apoptosis." (PMID 30318443, 2018). "Another explanation is that PTBP1 promotes the stability of these transcripts, a PTBP1 function observed in other cancers." (PMID 41214140, 2026). "PTBP1 has been identified as an oncogene in multiple cancer types, contributing to malignant progression through several molecular mechanisms." (PMID 41313521, 2025). "In conclusion, PTBP1, a splicing factor, is involved in a wide range of cellular biological processes, and research on PTBP1 is expected to find new ideas for treating cancer and other diseases." (PMID 40579921, 2025). "On the other hand, PTBP1 impairs SRSF3 autoregulation which likely explains the overexpression of both in primary cancers which predominantly express RIF1-S." (PMID 41489901, 2025). "As demonstrated by studies in some cancer cells and more recently in vascular smooth muscle cells, miR-124's proximal direct target, the RNA-binding protein PTBP1, is a crucial regulator of the effects of miR-124 on PH fibroblast proliferation and migration." (PMID 40225856, 2025). "Our findings further demonstrate that PTBP1 depletion enhances ferroptosis in Ishikawa and KLE EC cells, suggesting an anti-cancer effect of PTBP1 depletion in EC." (PMID 41313521, 2025). "PTBP1 plays a significant role in cancer progression by modulating alternative splicing, RNA stability, and translation." (PMID 40469179, 2025). "Aberrant PTBP1 function has been found to lead to aberrant acquired mis‐splicing, a process that promotes cancer." (PMID 40579921, 2025). "miR-506 can restore chemosensitivity to 5-fluorouracil (5-FU) in drug-resistant cancer cells by downregulating polypyrimidine tract-binding protein 1 (PTBP1) expression and suppressing glycolytic activity." (PMID 40248198, 2025). "Its role in different cell types and its relationship with cancer further emphasise the importance of PTBP1 in tumour biology." (PMID 40579921, 2025).
cancer (continued). "Elevated PTBP1 expression has been observed in multiple cancers, including CRC, where it promotes tumor growth and metastasis." (PMID 40469179, 2025). "By facilitating PTBP1-mediated alternative splicing of CD44 mRNA, CTC-490G23.2 upregulates the expression of CD44 variant isoform CD44v, which promotes cancer metastasis." (PMID 39937018, 2025). "Investigating the role of PTBP1 in different biological processes (e.g., development, regeneration, and disease genesis), especially its potential role in cancer, will help reveal its importance in regulating cellular functions." (PMID 40579921, 2025). "Knocking down Dio3os or PTBP1 led to a shift to unstable LDHA variants, emphasizing the Dio3os-PTBP1 interaction's role in maintaining LDHA mRNA stability through 3'UTR integrity and thereby enhancing glycolysis in drug-resistant cancer cells." (PMID 41235096, 2025). "Cancer development is a multigene, multistep, multistage process involving multiple genes, and cancers often have aberrant expression of PTBP1, a process that is closely related to cancer development." (PMID 40579921, 2025). "PTBP1 plays a pivotal role in mediating human carcinogenesis by regulating various aspects of cancer cell behavior, including growth, apoptosis, metastasis, and glycolysis." (PMID 41313521, 2025). "The current study suggests that research on the role of PTBP1 in cancer has excellent potential for clinical translation." (PMID 40579921, 2025). "In the analysis of cancer prognosis, we utilized the univariate Cox regression model to examine the relationship between PTBP1 expression and disease-specific survival (DSS) across 33 different cancers in the TCGA dataset." (PMID 38918441, 2024). "Compared to that in benign tumor tissues, the PTBP1 level was markedly increased in malignant tumor tissues of OC patients and slightly changed in paracarcinoma tissues of OC patients." (PMID 38071681, 2024). "As one of the hnRNPs, PTBP1 mainly regulates AS by binding their specific cis‐acting sequences in pre‐mRNA, and subsequently influences tumor progress in various cancers." (PMID 39287090, 2024). "The polypyrimidine tracts up- and downstream exon 12 are close enough to the 3′ and 5′ splice sites of this exon and the binding of PTBP1, whose level is increased in cancer, blocks the access of U2AF or U1." (PMID 38893242, 2024). "Compared to normal tissues, PTBP1 is significantly overexpressed and hypomethylated in various cancers." (PMID 38918441, 2024). "In the follow-up study, we focused on these eight cancers and studied the relationship between PTBP1 expression and tumor immune infiltration." (PMID 38918441, 2024). "PTBP1 can regulate the functions of apoptosis, proliferation, migration and invasion via different pathways and molecules in different kinds of cancer." (PMID 39422584, 2024). "From the previous study, we found that the expression of PTBP1 in 7 cancers is positively correlated with the prognosis of cancer patients' DSS." (PMID 38918441, 2024). "Experiments conducted in vitro and in vivo showed that PTBP1 accelerated the growth and metastasis of cancer cells." (PMID 38993556, 2024). "The analysis revealed that PTBP1 expression exhibited significant predictive power (AUC > 0.7) for prognostic survival at 1, 3, and 5 years in all three cancer types." (PMID 38918441, 2024). "The results showed PTBP1 is highly positively correlated with immune checkpoint genes in cancers such as KICH, LGG, and LIHC, while in THYM, the correlation is negative." (PMID 38918441, 2024). "Ultimately, the comprehensive characterization of PTBP1 in various cancer types paves the way for precision medicine approaches and personalized treatment strategies." (PMID 38918441, 2024). "Recent studies show that PTBP1 plays an important role in the occurrence and development of cancer, through regulating cell proliferation, glycolysis, and apoptosis, as well as angiogenesis." (PMID 38247832, 2024).
cancer (continued). "Conversely, the negative correlation observed in SARC suggests a distinct relationship between PTBP1 expression and immune cell infiltration in this particular cancer type." (PMID 38918441, 2024). "We identified cancer types in which PTBP1 expression significantly influenced patient DSS for further investigation." (PMID 38918441, 2024). "Our study elucidates the complex roles of PTBP1 in cancer biology, highlighting its value as a biomarker for a variety of cancer types." (PMID 38918441, 2024). "The results showed that these five mismatch repair-related genes were positively correlated with PTBP1 expression in most cancers (p < 0.01)." (PMID 38918441, 2024). "In this study, we found that PTBP1 was highly expressed in various cancers, and its methylation was significantly reduced in these cancers compared to normal tissues." (PMID 38918441, 2024). "We first performed GSEA on differential expression genes in the PTBP1 high and low expression groups and found significant activation of cell cycle, cancer-related signalling pathways in the PTBP1 high expression group." (PMID 38918441, 2024). "We found that PTBP1 exhibited prevalently increased expression in various cancer types and decreased expression in multiple cellular senescence models." (PMID 39057099, 2024). "The results of the immunohistochemical assay also confirmed that PTBP1 was upregulated in malignant tumor tissues compared to paracarcinoma tissues and benign tumor tissues." (PMID 38071681, 2024). "The reduction in PTBP1 mRNA and protein levels within these cancer cell lines was demonstrated and confirmed by RT-qPCR and Western blot analyses." (PMID 39057099, 2024). "Kaplan–Meier survival analysis revealed that patients with higher levels of PTBP1 had shorter overall survival (OS) and cancer‐specific survival (CSS) in both cohorts." (PMID 39287090, 2024). "To systematically elucidate the expression pattern of the splicing factor PTBP1 in cancers, we first analyzed the expression of PTBP1 in 33 types of cancers based on the TIMER database." (PMID 39057099, 2024). "For the selected cancer types, we generated Kaplan–Meier survival curves to compare the survival differences between the PTBP1 high and low expression groups." (PMID 38918441, 2024). "PTBP1 exhibited significantly increased expression in various cancer types including LUAD and showed consistently decreased expression in multiple cellular senescence models." (PMID 39057099, 2024). "Consequently, the silencing of PTBP1 may induce cellular senescence and suppress the release of tumor-associated SASP, indicating that the repression of PTBP1 may exert an anti-tumorigenic effect by promoting senescence while deterring its cancer-promoting potential." (PMID 39057099, 2024). "The expression profiles of PTBP1 across various cancers were derived from the TCGA, as well as the GTEx and CGGA databases." (PMID 38918441, 2024). "Recent research has highlighted the pivotal role of PTBP1 in the progression of various cancers, including GC." (PMID 39153986, 2024). "Taken together, these data demonstrate that PTBP1 expression is responsible for poor prognosis in GC patients and enriched in cancer stem-like GC cells." (PMID 36635500, 2023). "Overall, these findings strongly demonstrate that c-Myc is required for PTBP1 as an upstream regulator for maintaining cancer stem-like properties of GC cells." (PMID 36635500, 2023). "The polypyrimidine tract binding protein (PTBP1) is an RNA-binding protein involving in progressions of diverse cancers." (PMID 37724122, 2023). "PTBP1 plays an oncogenic role in many cancers by regulating the alternative splicing of critical genes." (PMID 36508323, 2023). "Overall, we indicated that PTBP1 participates in the maintenance of cancer stem-cell-like properties." (PMID 36635500, 2023). "NNMT, LDHB, and PTBP1 have been studied for promoting cancer development, but their synergistic effects with vemurafenib are not clear." (PMID 36829149, 2023).